EEF1B2 (eukaryotic translation elongation factor 1 beta 2)
Description:
Catalytic subunit of the guanine nucleotide exchange factor (GEF) (eEF1B subcomplex) of the eukaryotic elongation factor 1 complex (eEF1) (By similarity). Stimulates the exchange of GDP for GTP on elongation factor 1A (eEF1A), probably by displacing GDP from the nucleotide binding pocket in eEF1A (By similarity).
Synonyms: EEF1B; EF1B; EEF1B1
Tractability: PROTAC: UniProt records ubiquitination sites on it; ubiquitination databases record sites on it; its protein half-life has been measured.
Gene: Protein-coding gene on chromosome 2 (206,159,585 to 206,162,932, forward strand). Ensembl gene ENSG00000114942.
Subcellular location (Human Protein Atlas): Cytosol; Nucleoli fibrillar center
Pathways (Reactome):
Metabolism of proteins: Eukaryotic Translation Elongation
Gene Ontology:
Molecular function: protein binding; guanyl-nucleotide exchange factor activity; translation elongation factor activity
Biological process: translational elongation
Cellular component: cytoplasm; endoplasmic reticulum; nucleus; cytosol; eukaryotic translation elongation factor 1 complex
Genetic constraint (gnomAD): Loss-of-function variants: 12 observed, 28.26 expected, observed/expected ratio (o/e) 0.42, 90% interval 0.27 to 0.69. The upper end of that interval is the gene's LOEUF score, 0.69, which puts it in group 2 of 6, group 1 being the genes least tolerant of losing a copy. Missense variants: 234 observed, 280.95 expected, observed/expected ratio (o/e) 0.83, 90% interval 0.75 to 0.93. Synonymous variants: 83 observed, 103.19 expected, observed/expected ratio (o/e) 0.8, 90% interval 0.67 to 0.96.
Homologues: Orthologues: chimpanzee EEF1B2 (100% identical), macaque EEF1B2 (99% identical), pig EEF1B2 (99% identical), dog EEF1B2 (98% identical), guinea pig EEF1B2 (96% identical), mouse Eef1b2 (96% identical), tropical clawed frog eef1b2 (87% identical), zebrafish eef1b2 (82% identical), rat AABR07006688.2 (50% identical), Caenorhabditis elegans eef-1B.1 (47% identical), Drosophila melanogaster eEF1beta (47% identical), Drosophila melanogaster eEF1delta (44% identical). Paralogues in human: EEF1D (61% identical), EFCC1 (24% identical).
Diseases named in the same sentence as EEF1B2 in open-access papers:
EEF1B2 is named in the same sentence as 40 diseases in open-access papers, as found by Europe PMC text mining. Sharing a sentence is not in itself a finding about the gene and the disease. The quoted sentences say what the papers report.
lung carcinoma (4 papers, 2018 to 2024). "Overexpression of Eef1b2 and Hnrnpa1 has been previously linked with cancer progression and poor prognosis in breast and lung cancer." (PMID 39165691, 2024). "The eukaryotic translation elongation factors EEF1B2 and EEF2 are down-regulated in breast, esophageal, and lung cancers while EEF1B2 is found with repression in some other cancer types, such as head and neck, leukemia, and pancreatic cancer." (PMID 31242667, 2019). "EEF1B2 was found to be overexpressed in lung cancer in humans." (PMID 38878096, 2024). "Overexpression of most factors predicted a poor prognosis in breast (EEF1D, EEF1E1, and EEF2) and lung cancer (EEF1A2, EEF1B2, EEF1G, EEF1E1) in KM analysis." (PMID 29342219, 2018). "Overexpression of many factors predicted poor prognosis in breast (EEF1D, EEF1E1, EEF2) and lung cancer (EEF1A2, EEF1B2, EEF1G, EEF1E1)." (PMID 29342219, 2018).
Intellectual disability (2 papers, 2016 to 2024). "Conversely, intellectual disability is caused by the loss of function in the EEF1B2 gene." (PMID 38878096, 2024). "Moreover, EEF1B2 has been implicated in intellectual disability and tumorigenesis." (PMID 38878096, 2024). "While the role of EEF1B2 in intellectual disability and tumorigenesis is well established, its function in the bone-fat switch of BMSCs is still largely unexplored." (PMID 38878096, 2024).
invasive breast carcinoma (2 papers, 2018 to 2024). A carcinoma that infiltrates the breast parenchyma. "Ma Breast and Finak Breast, showed reduced levels of EEF1B2 in invasive ductal breast carcinoma and invasive breast carcinoma respectively, compared to the normal." (PMID 29342219, 2018).
pancreatic cancer (2 papers, 2018 to 2019). "In pancreatic cancer, the mRNA levels of EEF1A1, EEF1A2, EEF1B2, EEF1D and EEF1E1 were found to be significantly downregulated, as shown by Oncomine analysis." (PMID 29342219, 2018).
Alzheimer disease (1 paper, 2022). A progressive, neurodegenerative disease characterized by loss of function and death of nerve cells in several areas of the brain leading to loss of cognitive function such as memory and language. "In addition, EEF1B2 was also a potential biomarker for the pathogenesis of Alzheimer’s disease." (PMID 35884735, 2022).
autosomal recessive intellectual disability (1 paper, 2022). "It was reported that a novel biallelic loss of EEF1B2 function was reported to be associated with autosomal recessive intellectual disability." (PMID 35884735, 2022).
Burkitt lymphoma (1 paper, 2018). A rare form of malignant mature B-cell non-Hodgkin lymphoma. "For EEF1B2, three studies from Brune’s dataset showed elevated transcript levels in follicular lymphoma, diffuse large B-Cell lymphoma and, in Burkitt's lymphoma." (PMID 29342219, 2018).
cervical cancer (1 paper, 2021). A primary or metastatic malignant neoplasm involving the cervix. "By observing the difference in the expression levels of key genes in the different types of cervical cancer and normal tissues, we found that most genes, such as RPS27A, RPS3, and EEF1B2, were significantly expressed in cervical cancer." (PMID 34796111, 2021).
colorectal cancer (1 paper, 2018). A primary or metastatic malignant neoplasm that affects the colon or rectum. "SurvExpress analysis revealed significantly reduced mRNA levels of EEF1A1, EEF1B2, EEF1E1, EEF1G and EEF2 in the high-risk group, in colorectal cancer and, predicted poor survival." (PMID 29342219, 2018). "Oncomine analysis of colorectal cancer with the pre-specified thresholds didn’t return any datasets with significant difference in mRNA levels, for EEF1A1, EEF1A2, EEF1B2, EEF1G and EEF2." (PMID 29342219, 2018).
hypopharyngeal squamous cell carcinoma (1 paper, 2018). "For tumors of head and neck type, Oncomine analysis revealed that mRNA levels of EEF1A2 and EEF1B2 were significantly lower in tongue squamous cell carcinoma, salivary gland adenoid cystic carcinoma and hypopharyngeal squamous cell carcinoma, respectively." (PMID 29342219, 2018).
kidney cancer (1 paper, 2018). Primary or metastatic malignant neoplasm involving the kidney. "Oncomine analysis of kidney cancer revealed that, EEF1A2 and EEF1B2 mRNA levels were upregulated in cancer samples." (PMID 29342219, 2018).
kidney clear cell carcinoma (1 paper, 2018). "As per TCGA analysis, expression levels of EEF1A1, EEF1B2, EEF1G, EEF1D and EEF2 were significantly upregulated in kidney clear cell carcinoma while that of EEF1E1 was downregulated." (PMID 29342219, 2018).
oligodendroglioma (1 paper, 2018). A well-differentiated (WHO grade II), diffusely infiltrating neuroglial tumor, typically located in the cerebral hemispheres. "For EEF1B2, significantly elevated levels were observed in atypical teratoid/rhabdoid tumor and oligodendroglioma in Pomeroy’s dataset." (PMID 29342219, 2018).
osteoporosis (1 paper, 2024). A condition of reduced bone mass, with decreased cortical thickness and a decrease in the number and size of the trabeculae of cancellous bone (but normal chemical composition), resulting in increased fracture incidence. "In vivo, the excessive expression of EEF1B2 can mitigate bone loss and decrease the amount of fat in the bone marrow of mice with osteoporosis." (PMID 38878096, 2024). "Furthermore, the excessive expression of EEF1B2 in the tibias has the potential to mitigate bone loss and decrease marrow adiposity in mice with osteoporosis." (PMID 38878096, 2024). "In order to elucidate the function of EEF1B2 in the determination of BMSCs cell destiny in vivo, a model of osteoporosis was generated through the removal of ovaries in mice (OVX mice)." (PMID 38878096, 2024). "Taken together, these data show that EEF1B2 regulates β-catenin activity to restore the equilibrium between osteogenesis and adipogenesis, suggesting the involvement of Wnt/β-catenin signaling in the osteogenic and adipogenic differentiation of BMSCs during the progression of osteoporosis." (PMID 38878096, 2024). "This study has provided confirmation that the overexpression of EEF1B2 has the potential to enhance bone formation and decrease the accumulation of fat in the bone marrow of OVX mice, offering valuable insights for the treatment of osteoporosis." (PMID 38878096, 2024).
tumor (7 papers, 2009 to 2024). "XPO1 exhibited significant exon skip alterations in tumors compared to adjacent normal samples, while the alternative 3’ change of EEF1B2 showed a significant difference between tumor and adjacent normal samples." (PMID 37735421, 2023). "For EEF1B2, 11 datasets showed increased expression in tumor tissues, whereas nine datasets showed significantly reduced levels in tumors, compared to control tissue." (PMID 29342219, 2018). "In the rS-pS group, some interesting genes with deviating correlation between early and late stages including PSMB4 (proteasome subunit beta type-4) with high correlation in the late stage and EEF1B2 (elongation factor 1-beta) with high correlation in the early stage of tumor tissue were identified." (PMID 33384992, 2020). "Higher EEF1B2 levels correlated with better OS in all tumor stages." (PMID 29342219, 2018). "EEF1B2, EEF1G, EEF1D, EEF1E1 and EEF2, presented increased transcript levels in tumor group compared to normal, the most prominent being EEF1E1." (PMID 29342219, 2018). "TCGA analysis further confirmed that mRNA levels of EEF1A1, EEF1A2, EEF1B2, EEF1G and EEF2 were significantly downregulated in tumor tissues than normal." (PMID 29342219, 2018).
cancer (6 papers, 2016 to 2024). A tumor composed of atypical neoplastic, often pleomorphic cells that invade other tissues. "Conversely, increased EEF1B2 expression has been observed in the majority of cancer types." (PMID 37922300, 2023). "Higher expression of EEF1A2, EEF1B2, EEF1G, EEF1D, EEF1E1 and EEF2 was observed in most of the cancer types, whereas reverse trend was observed for EEF1A1." (PMID 29342219, 2018). "Earlier studies have hinted at the pro-tumorigenic role of EEF1B2 and EEF2 in cancers which was evident in the present study also." (PMID 29342219, 2018). "Keeping these lacunae in hindsight, we have undertaken a pan-cancer approach for comprehensive analysis of expression levels of seven elongation factors namely, EEF1A1, EEF1A2, EEF1B2, EEF1G, EEF1D, EEF1E1 and EEF2, using publicly available databases (Oncomine and TCGA)." (PMID 29342219, 2018). "In addition to EEF1A2, other translation factors EEF1B2, EEF1G, EEF1D, EEF1E1, and EEF2 were also found to be frequently overexpressed in different cancers." (PMID 29342219, 2018). "Likewise, translation initiation (EIF1A, EIF4A, EIF4G) and elongation (EEF1B2, EEF2) factors are well-known to play a role in cancer, as well as ribosome biogenesis related factors, like the pseudouridine synthase dyskerin and the 2′-O-methyltransferase fibrillarin." (PMID 32046192, 2020). "Translation elongation factor EEF1B2 and translation initiation factor EIF5A have non-canonical functions unrelated to protein synthesis, which are reported to control cancer cell proliferation." (PMID 26894977, 2016).
adenocarcinoma (1 paper, 2018). A common cancer characterized by the presence of malignant glandular cells. "Likewise, elevated mRNA levels of EEF1B2, EEF1G and EEF2 were significantly correlated with worse survival outcome in adenocarcinoma." (PMID 29342219, 2018).
EEF1B2 also shares sentences with these, for which no sentence is quoted: viral infection (2 papers); breast carcinoma (1); clear cell carcinoma (1); COVID-19 (1); diffuse large B-cell lymphoma (1); endometrioid carcinoma (1); follicular lymphoma (1); glioma (1); infection (1); invasive ductal breast carcinoma (1); leukemia (1); lung adenocarcinoma (1); nematode infection (1); neurological disorders (1); osteosarcoma (1); ovarian carcinoma (1); ovarian tumors (1); preeclampsia (1); rhabdoid tumor (1); salivary gland adenoid cystic carcinoma (1); serous adenocarcinoma (1); Stroke (1); tongue squamous cell carcinoma (1).